SNORA38B (small nucleolar RNA, H/ACA box 38B)
Gene: Small nucleolar RNA gene on chromosome 17 (67,740,669 to 67,740,799, forward strand). Ensembl gene ENSG00000200394.
Gene Ontology:
Biological process: RNA processing
Cellular component: Cajal body; nucleolus
Homologues: Orthologues: chimpanzee SNORA38B (100% identical), macaque SNORA38B (96% identical), mouse Gm22944 (73% identical), rat LOC120101256 (64% identical). Paralogues in human: SNORA38 (84% identical).
Diseases named in the same sentence as SNORA38B in open-access papers:
SNORA38B is named in the same sentence as 5 diseases in open-access papers, as found by Europe PMC text mining. Sharing a sentence is not in itself a finding about the gene and the disease. The quoted sentences say what the papers report.
breast carcinoma (1 paper, 2023). "SNORA38B was reported to have a potential role in the PI3K-AKT/ERK/mTOR pathway in breast cancer." (PMID 37686617, 2023).
schizophrenia (1 paper, 2019). A major psychotic disorder characterized by abnormalities in the perception or expression of reality. "Although non-coding RNAs such as small nucleolar RNAs (snoRNAs), microRNAs and long non-coding RNAs (LncRNAs), have been studied in disease etiology, the involvement of SNORA38B, SNORA68, SNORA23, SNORA20, and SNORA3A in the pathogenesis of schizophrenia has yet to be reported." (PMID 30967896, 2019).
tumor (2 papers, 2024 to 2025). "For example, SNORA38B promotes IL-10 secretion in tumor cells, leading to the recruitment of CD4+FOXP3+regulatory T cells and reduced infiltration of CD3+CD8+T cells in the TME of non-small cell lung cancer (NSCLC), thereby promoting tumor progression." (PMID 41019058, 2025). "SNORA38B plays a role in promoting tumor progression in NSCLC by directly binding to E2F transcription factor (E2F1) and regulating the GAB2/AKT/mTOR pathway thereby contributing to the development of an immunosuppressive tumor microenvironment." (PMID 38406265, 2024).
cancer (1 paper, 2024). A tumor composed of atypical neoplastic, often pleomorphic cells that invade other tissues. "Altogether, the findings jointly substantiate that SNORA38B is an oncogene that drives cancer by enhancing tumor growth and suppressing cancer-regulating immune activity." (PMID 38474168, 2024).
SNORA38B also shares sentences with these, for which no sentence is quoted: glioblastoma (1 paper).